MAGI2 (membrane associated guanylate kinase, WW and PDZ domain containing 2)
Diseases named in the same sentence as MAGI2 in open-access papers (continued):
Sharing a sentence is not in itself a finding about the gene and the disease.
neurodegenerative disease (1 paper, 2022). A disorder of the central nervous system characterized by gradual and progressive loss of neural tissue and neurologic function. "Magi2, Kif5b, Sqstm1 and Rap1a are associated neuronal development and neurite outgrowth, and some have previously been implicated in the pathogenesis of neurodegenerative diseases." (PMID 36089582, 2022).
prostate (1 paper, 2021). "A role of MAGI2 in prostate tumorigenesis has been also evaluated; mutations in MAGI2 contribute to prostate carcinogenesis by driving AKT phosphorylation and altering PI3K signaling, thus disrupting PTEN signaling." (PMID 34198584, 2021).
MAGI2 also shares sentences with these, for which no sentence is quoted: Anxiety (3 papers); Crohn disease (2); glomerulopathies (2); kidney failure (2); Parkinson disease (2); type 2 diabetes (2); Allergy (1); asthma (1); Ataxia (1); bipolar disorder (1); Choreoathetosis (1); ciliopathies (1); cystic kidney disease (1); eating disorder (1); epilepsy syndrome (1); hepatocellular carcinoma (1); Huntington disease (1); IgA nephropathy (1); inflammatory bowel disease (1); insulin-dependent diabetes mellitus (1); Intellectual disability (1); leukemia (1); melanoma (1); movement disorder (1); myoclonic epilepsy (1); nephrotic syndrome type 15 (1); neurodevelopmental disorder (1); neurological disorders (1); ovarian carcinoma (1); pancreatic cancer (1).
A further 6 diseases each share a sentence with MAGI2 in 1 paper.